PAX5 (paired box 5)
Diseases named in the same sentence as PAX5 in open-access papers (continued):
Sharing a sentence is not in itself a finding about the gene and the disease.
leukemia (continued). "However, it is important to note that, in human leukemias like in mice, PD-1 expression is not solely dependent on PAX5 activity." (PMID 41283237, 2025). "Because SIRT7 activity strongly increased Pax5 levels in B cell progenitors, human B-ALL samples and cell lines, we propose that developing SIRT7-activating compounds to stimulate Pax5 functions may provide a basis for leukemia therapies." (PMID 39424985, 2024). "Unfortunately, a leukemia or historical remission sample from the father, which could have revealed presence of the PAX5 deletion at time of diagnosis, was not available." (PMID 37543654, 2023). "Therefore, the timing of infection does not appear to impact leukemia development in Pax5+/− mice with exposure to an immune stressor (i.e., housing in a conventional, non-SPF, facility) representing the triggering event." (PMID 37620322, 2023). "Indeed, when additional mutations were separately introduced into the zebrafish orthologs of the human PAX5 and CDKN2A/B genes, which are deleted in a quarter of the E::R leukemias, the incidence increased to 15% and 7%, respectively, which is similar to what has been observed in mice." (PMID 38136366, 2023). "In addition, pro-B cells increased abnormally in the preleukemic phases because of the effect of PAX5-ELN, which may induce leukemia." (PMID 37335685, 2023). "However, Pax5 heterozygous mice exhibit normal B-cell development and is not sufficient to induce leukemia in the absence of other oncogenic lesions." (PMID 34771671, 2021). "An important aspect that should be taken into consideration is that, although our data show that Pax5 indeed regulates IL6 expression, it cannot be rouled out that the microenvironment, following infections and/or leukemia, might also contribute to the observed IL6 increase." (PMID 33154497, 2020). "The typically prolonged latency from birth to clinically manifest leukemia indicates that ETV6-RUNX1 alone requires cooperating genetic events to induce leukemia, including deletion of the non-rearranged ETV6 allele, focal deletion of PAX5 and mutation of WHSC1." (PMID 34501239, 2021). "Interestingly, AID is not required for leukemia development in the Pax5+/− mouse model." (PMID 33507341, 2021). "However, key lineage specific transcription factors (PU.1, GATA-1, IKAROS, PAX5) were not differentially expressed in HSPCs, suggesting that the immunocompetent leukemia microenvironment may contribute to deregulation of hematopoiesis." (PMID 33154494, 2020). "However, transplantation of Pax5± pre-BII cells was not sufficient to initiate leukemia development, likely due to limited size of the persisting cell population that in part differentiated into mature B-cells, before additional potentially RAG-mediated somatic mutations could take place." (PMID 40394211, 2025). "Different primer combinations failed to amplify the reciprocal PML-PAX5 fusion transcript, indicating that the PAX5-PML fusion manages the initiation of leukemia." (PMID 37335685, 2023). "As expected, leukemias expressed T-cell specific markers (Lck, CD4, CD8, and TCRα and β), but not B-cell specific genes (e.g. Pax5, CD79a or IgM), indicating they were of T-cell origin." (PMID 35581375, 2022). "Consistently, tumor Pax5-het/Aid-het and Pax5-het/Aid-KO pro-B cells grow independent of IL7 and can initiate leukemia in secondary transplant recipients." (PMID 31804490, 2019). "Molecular profiling of isolated leukemia cells confirmed expression of lymphoid (rag1 and rag2) and T-cell specific (lck and tcrβ-C2) markers, with no significant upregulation of B-cell genes (pax5, igD-VH1, and igM-VH1), indicating that PRL-3 did not alter leukemia lineage identity." (PMID 40463094, 2025). "Germline PAX5 deletions have not yet been described in patients with BCP-ALL but considering the recurrence of somatic PAX5 deletions in BCP-ALL, the germline deletion in our patient likely contributed to leukemia development." (PMID 37543654, 2023).
leukemia (continued). "Although the transformation process in Pax5+/− B-ALL is independent of AID, in Irf4−/− leukemias, AID might be playing a role in the acquisition of secondary mutations." (PMID 35886910, 2022).
lymphoma (71 papers, 2006 to 2026). A malignant (clonal) proliferation of B- lymphocytes or T- lymphocytes which involves the lymph nodes, bone marrow and/or extranodal sites. "This explains that one of the reasons for the formation of aggressive PAX5-deficient lymphomas with a phenotype similar to B cell progenitors is probably due to a dedifferentiation process." (PMID 32604737, 2020). "Pax-5, an essential transcription factor for B lymphocyte development, has been linked with the development and progression of lymphoid cancers and carcinoma." (PMID 28076843, 2017). "Next, we checked whether PAX5-TSS2mut incorporated in SUDHL10 lymphoma cells, using Cas9-driven HDR, would cause 5.8S + 40 rRNA accumulation." (PMID 38049665, 2023). "The retrospective study used a primary panel of monoclonal antibodies consisting of CD3 and CD5, CD20, CD10, CD45, PAX-5 and Ki-67 on 88 lymphoma cases." (PMID 41960458, 2026). "Due to the critical role of PAX-5 in maintaining B-cell function, its reduction or inactivation may favor this loss of identity and differentiation to macrophages, which supports the possibility of a lymphoma undergoing transdifferentiation into a histiocytic/dendritic cells neoplasm." (PMID 40983970, 2025). "While PAX5 is often a secondary player in lymphomas, its genetic and epigenetic alterations are significant contributors to disease initiation, progression, and patient prognosis." (PMID 40506992, 2025). "Genetic modulations involving PAX5 gene are also reflected in the molecular, clinical and pathological heterogeneity of B-cell-derived lymphomas and leukemia at various degrees of differentiation." (PMID 40506992, 2025). "For instance, PAX5 is employed as an immunohistochemical marker for the diagnosis and subtyping of lymphomas." (PMID 40506992, 2025). "Overall, PAX5 stands as versatile a contributor across lymphoma subtypes, particularly as an oncogenic driver in DLBCL and a prognostic marker in MCL." (PMID 40506992, 2025). "In such cases, markers like PAX5 and/or CD79a can be used for any lymphoma exhibiting Hodgkin or non-Hodgkin lymphoma features." (PMID 40428800, 2025). "Germline PAX5 alterations, including sequence variants and deletions, are associated with a selective susceptibility to BCP‐ALL and lymphomas, based on a limited number of affected families worldwide." (PMID 40981401, 2025). "PAX5 is extensively studied in lymphoma and lymphocytic leukemia, working as an oncogene related to developmental defects in B cells." (PMID 38398215, 2024). "For the differential diagnosis of other lymphomas, the immunohistochemical staining of Bcl-6 (+++), ki-67 (+++), c-myc (+), Pax-5 (++), MUM1 (+), CD5(+), and CD10 (−) was performed." (PMID 40453362, 2024). "Characteristics of feline lymphomas categorized by anatomical subtype, including comprehensive B-cell lineage markers (PAX5, CD20, and CD79α)." (PMID 39619931, 2024). "Evaluating the presence of CD15 and CD20, in addition to other markers such as CD30 and PAX5, enhances the precision of diagnosing cHL and assists in differentiating it from other types of lymphomas." (PMID 39669843, 2024). "Other highly malignant tumors such as metastatic melanoma (SOX-10 marker) and lymphoma (CD-19, PAX-5, terminal deoxynucleotidyl transferase (TdT) markers, etc.)should also be considered in differentials." (PMID 37113364, 2023). "At many loci, we find lymphoma transformation-associated aSHM cluster around boundaries of TADs containing known aSHM targets including DTX1, BCL2 and PAX5." (PMID 38049665, 2023). "Immunolabeling on RSC and CB was compared for lymphoid markers (CD3 and PAX5) in 53 lymphomas and 4 chylous effusions from dogs and cats." (PMID 36851461, 2023). "Five genes, all with variants in two cases, were shown to be associated with lymphoma pathogenesis (ID3, PAX5, TBL1XR1, IGLL5 and APC) in previous studies." (PMID 35205758, 2022).
lymphoma (continued). "Given its pivotal regulatory role in B-cell development, PAX5 also represents a potent oncogene in hematological cancers, particularly lymphoma and lymphocytic leukemia." (PMID 36077495, 2022). "For example, family studies have identified a PAX5 G183S germline mutation conferring susceptibility to B-ALL, which corresponds to somatic mutations detected in pediatric B-ALL and lymphoma." (PMID 31439692, 2019). "Functional studies have shown that Pax-5 behaves as a potent oncogene in most types of lymphoma and lymphocytic leukemia." (PMID 28076843, 2017). "Pax-5 expression has also been reported in various cancer cells, including medulloblastoma, lymphoma, small-cell lung carcinoma, and neuroblastoma." (PMID 27490539, 2016). "Pathologic analysis showed infiltration of lymphoma cells in spleens of these mice and these tumor cells expressed Pax5, a B cell specific transcription factor." (PMID 23626802, 2013). "Immunostains for CD20, CD79a, and PAX-5 showed strong positive staining of the atypical cells, confirming B-cell origin and resulting in the diagnosis of lymphoma, large B-cell type." (PMID 29147306, 2012). "The lymphomas that arose in founder 24 were histologically indistinguishable from typical line 17 lymphomas and like these were Pax5+ and BCL6- by immunostaining." (PMID 16563162, 2006). "However, PAX5 expression has been found in some T-lymphomas, myeloid neoplasms and in a small percentage of undifferentiated non-hematolymphoid tumors." (PMID 40506992, 2025). "Morphological characteristics in H&E staining were examined and immunohistochemistry for CD3 and PAX5 was performed to classify the splenic lymphoma cases according to the revised European–American lymphoma classification adopted by the World Health Organization." (PMID 37104402, 2023). "In feline lymphoma cases, the performance of the PAX5 antibody on RSC was unsatisfactory." (PMID 36851461, 2023). "Furthermore, even in wild-type mice, deletion of any one of the tumor suppressor genes Pax5, Sfpi1, Ikzf1, Pten or Cdkn2a has been reported specifically in irradiated animals in copy number analyses of lymphomas, acute myeloid leukemia and thymic lymphoma." (PMID 37117033, 2023). "Aberrant somatic point mutations may also occur in PCNS-DLBCLs involving MYC and PAX5, also known as B-cell-specific activator protein (BSAP), which then become mutated oncogenes that contribute to the pathogenesis of lymphomas." (PMID 36992464, 2023). "Specific expression of PAX5 in B cells may serve as a biomarker in the diagnosis and prognosis of B cell leukemias and lymphomas." (PMID 36544484, 2022). "According to histopathological evaluation and immunofluorescence staining for PAX5 of the original spontaneous lymphomas, OPL239 was derived from an early-stage DLBCL that still preserved the nodular architecture, whereas OPL241 originated from a more advanced DLBCL, already spread in the spleen." (PMID 36503430, 2022). "Finally, PAX5 has been associated with aggressive B-cell non-Hodgkin’s lymphoma and APC with adult T-cell leukemia/lymphoma." (PMID 35205758, 2022). "The involvement of Pax5, AML1 and other oncogenes mutations associated with these features previously presented may lead to the full-blown lymphoma due to IPSID, but their role is still uncertain in the pathogenesis." (PMID 34270561, 2021). "The paired box gene 5 (PAX5) is extensively studied in lymphoma and lymphocytic leukemia." (PMID 33403035, 2021). "We now know that Pax-5 expression is found in a variety of cell types and non-lymphoid cancers such as: neuroblastoma, rhabdomyosarcoma, merkel- and small-cell carcinomas, oral carcinomas, colorectal carcinoma, neuroendocrine carcinoma, bladder carcinoma, lung carcinoma, liver carcinoma." (PMID 28076843, 2017).
lymphoma (continued). "The lower levels of PAX5 in DLBCL tissues compared with FL tissues further indicate that the microenvironment in aggressive lymphomas may be less supportive of normal B-cell differentiation, potentially contributing to immune evasion and poorer response to therapy." (PMID 41373408, 2025). "Given that both deletion and point mutation of PAX5-TSS2 lead to stronger interactions between the PAX5 enhancer region and the ZCCHC7 promoter and a corresponding increase in ZCCHC7 mRNA expression, we postulate that PAX5 promoter mutations in lymphoma cells increase ZCCHC7 expression." (PMID 38049665, 2023). "However, PAX5 is mostly regarded as a tumor suppressor in non-lymphoid cancers." (PMID 33403035, 2021). "This double staining was so far reported in Kiyasu’s study of 1091 patients with DLBCL14, NOS and Chen’s study of various lymphoma subtypes, including 66 patients with DLBCL, NOS33, but both studies used only PD-L1/PAX5 staining." (PMID 38378036, 2024). "According to our study, PAX5 and CD3 markers are strongly recommended for diagnosing feline lymphoma." (PMID 39619931, 2024). "Notably, this mechanism could explain the ZCCHC7 overexpression that we observe in lymphomas that do not harbor PAX5/ZCCHC7 copy number gains but have PAX5-ZCCHC7 SE mutations." (PMID 38049665, 2023). "In this study, lymphoid markers (CD3 and PAX5) were simultaneously studied in RSC and matched CB from 53 lymphomas and 4 chylous (lymphocyte-rich) effusions from dogs and cats." (PMID 36851461, 2023). "Atypical lymphoid infiltrates, consistent with lymphoma in histopathology and the classical immunoexpression pattern, showed positive CD15, CD30, PAX5." (PMID 34089301, 2022). "Analysis of BL and DLBCL tumors revealed that apart from the IG genes, main loci of AID mutations were active enhancers of genes with a known role in lymphoma: BCL6, PAX5, ETS1, CIITA, CXCR4." (PMID 34210001, 2021). "In this study, we described the first evidence of Pax-5 3′UTR editing and its effects on translation in human B-cells and lymphoid cancer lesions." (PMID 35011638, 2021). "The CD19 negative DLBCL were characterized further for other B cell lineage and lymphoma markers including CD20, PAX5, CD138, BCL2, BCL6, BCL10 and MUM1 using immunohistochemistry." (PMID 28484276, 2017). "FISH analyses using BAC clones covering lymphoma breakpoints (BCL2, BCL6, BCL11A, CCND1, CCND3, IG-H/K/L, JAK2, LMO2, MYC, PAX5, REL) all tested normal, excluding rearrangements at these loci." (PMID 26599546, 2015). "FOXP1 was already described as fused to either the PAX5 or the ABL1 gene in B-ALL, and to the immunoglobulin heavy chain locus in lymphomas." (PMID 24893616, 2014). "Positivity for CD20, PAX5, and BCL 2, expression of surface kappa light chains and dim CD20 by flow cytometry again suggest a more mature lymphoma." (PMID 23533894, 2013). "Despite the initial diagnosis of lymphoma, immunohistochemistry demonstrated that the neoplastic cells were negative for multiple lineage-specific markers, including CD3, Pax5, CD20, and cytokeratin, but showed strong MUM-1 positivity in mitotically active cells." (PMID 42076756, 2026). "Initial IHC results excluded lymphoma and nephroblastoma as neoplastic cells lacked expression of CD3 and PAX5 for lymphoma and Wilms’ tumor 1 for nephroblastoma." (PMID 40948633, 2025). "Generally, these lymphomas lack CD45, PAX5, and CD20 markers." (PMID 40428800, 2025). "As these are T-cell-derived neoplasms with monoclonal expression of the TCR, PAX5 is negative and is often used as a marker in differential diagnostics with other lymphomas, that morphologically overlap with ALCL, such as Hodgkin’s lymphoma, characterized by weak PAX5 expression." (PMID 40506992, 2025).
lymphoma (continued). "Molecular pathology features: According to the European Neuro-Oncology Association guidelines for the diagnosis of immunocompetent primary lymphomas, the immunohistochemical features of diffuse large B-cell lymphoma of the central nervous system are marked by CD10, CD19, CD20, PAX-5, BCL-6, MUM1." (PMID 36961159, 2023). "MPO and PAX-5 staining revealed the lack of B cells, granulocytes, and monocytes in spleen lymphomas." (PMID 35852337, 2022). "By immunohistochemistry, the lymphoma cells were positive for PAX‐5, CD5 (partial/weak) (Panel E: PAX‐5/CD5 dual stain, original magnification ×400), IgD (original magnification ×400), DBA.44 (original magnification ×400), and negative for Cyclin D1, SOX11, IgG, and BRAF V600E." (PMID 35845277, 2021). "In line with this, translocations in lymphomas and leukemias occur either in oncogenes active at some stages of B cell maturation (like BCL2, MYC) or in genes orchestrating B cell development and activation (e.g., CD79B, PAX5)." (PMID 34210001, 2021). "Their IHC results showed that lymphoma cells were positive for PAX5 and CD20, and negative for CD138 and light chains." (PMID 34503477, 2021). "Lymphoma tissues consisted of different populations of lymphocytes, centroblasts, and immunoblasts, many with plasmacytoid differentiation with heterogenous expression of both CD20 and Pax5, showing tumor cells at different stages of differentiation." (PMID 30001436, 2018). "CD19 is a downstream target of PAX5, so it is not immediately obvious how lymphomas can maintain CD19 expression without PAX5 function." (PMID 28484276, 2017). "MMTV-RARαG303E lymphomas were high grade Pax-5+, surface H+L Ig negative, CD69+ and BCL6- and cytologically and phenotypically resembled human adult high grade (Burkitt's or lymphoblastic) lymphomas." (PMID 16563162, 2006). "Consistently, lymphomas were Pax5+, B220+, CD43+, AA41+, CD69+ and negative for surface heavy or light chain immunoglobulins, CD5, CD4, CD8, CD23, CD21, BCL6." (PMID 16563162, 2006). "Since EBF1, PAX5, and MYC are essential for B cell development, their ectopic expression or mutants may lead to abnormal B cell development and hematologic neoplasms, such as B-lymphoid leukemia and lymphoma." (PMID 38318177, 2024). "Moreover, the homogenous expression of either CD3 or PAX5 will not apply to null-cell (non-B-cell and non-T-cell) lymphoma." (PMID 37104402, 2023). "The analysis of PAX5 was limited to an immunohistochemistry analysis and although reduced there may be sufficient PAX5 present in the CD19 positive lymphomas classified as PAX5 negative to allow CD19 expression." (PMID 28484276, 2017). "However, immunohistochemistry for CD3 and PAX5 may not allow for easy distinctions between some cases of lymphoma (especially follicular lymphoma) and nodular hyperplasia." (PMID 37104402, 2023). "Histopathological analysis confirmed non-germinal center diffuse large B-cell lymphoma (DLBCL) within the hematoma, supported by immunohistochemical and FISH findings, including CD20(+), PAX-5(+), MUM-1(+), and Ki-67(+, 60%)." (PMID 41019131, 2025). "CD45.2+ lymphoma cells were negative for all evaluated B‐cell markers, including CD19, CD20, and Pax5, and instead expressed T‐cell markers CD3, Thy1, and TCRβ." (PMID 35510955, 2022). "In CLL/SLL, MCL, MZL, FL, and HG B-NHL cases, the lymphoma cells were positive for CD20 and PAX5 and negative for CD38 and CD138 by IHC." (PMID 34879826, 2021).